EDN3 (endothelin 3)
Diseases named in the same sentence as EDN3 in open-access papers (continued):
Sharing a sentence is not in itself a finding about the gene and the disease.
breast carcinoma (continued). "In breast cancer, cervical cancer, colorectal cancer, glioma and papillary thyroid cancer, the expression of EDN3 gene is significantly down-regulated, which may be regulated by epigenetics." (PMID 36824133, 2023). "In breast cancer, cervical cancer, colorectal cancer and glioma, the expression of EDN3 gene is significantly down-regulated, which may be regulated by epigenetics." (PMID 36824133, 2023). "Knocking down the EDNRB gene in breast cancer cells altered invasiveness toward endothelin 3 (ET3), and we observed EDNRB isoform-specific regulation of breast cancer cell invasion and cell signaling, as well as isoform- and subtype-specific differences in breast cancer patient survival." (PMID 32201539, 2020). "Because the downstream effects of EDNRB are likely affected by the presence of its major ligands, ET1 and ET3 (encoded for by EDN1 and EDN3, respectively), we also analyzed survival in breast cancer subtypes by relative combined expression of EDNRB/EDN3 and EDNRB/EDN1 mRNA." (PMID 32201539, 2020). "Next, we analysed EDN3 promoter methylation in primary breast cancer as well." (PMID 19527488, 2009). "Therefore, we started a detailed analysis on EDN3 expression and its potential implication in human breast cancer." (PMID 19527488, 2009). "EDN3 promoter methylation was analysed by methylation-specific PCR in breast cell lines (n = 6) before and after demethylating treatment, normal breast tissues (n = 17) and primary breast carcinomas (n = 128)." (PMID 19527488, 2009). "In breast carcinomas, downregulation of EDN3 expression by FC2 could be detected in 60 of 77 cases (78%; median: 21-fold) as compared with the normal breast reference standard." (PMID 19527488, 2009). "EDN3 expression, in contrast to abundant EDN1 and EDN2 expression, becomes frequently inactivated by promoter methylation in human breast cancer, potentially causing aberrant activation of the ET-axis, which in turn may promote this disease." (PMID 19527488, 2009). "Furthermore, we identified the molecular mechanism by which EDN3 expression is deregulated in breast carcinomas." (PMID 19527488, 2009). "A breast cancer dot blot cDNA array was then hybridised with the same EDN3-specific probe." (PMID 19527488, 2009). "Therefore, upregulation of EDN1 appears to coincide with downregulation of EDN3 in breast cancer cell lines." (PMID 19527488, 2009). "Because we have previously found that EDN3 mRNA expression is downregulated in primary breast carcinomas as compared with normal breast tissues, we aimed in this report to provide the first comprehensive analysis of EDN3 expression and its potential implication in human breast cancer." (PMID 19527488, 2009). "Forced EDN3 re-expression by DNA demethylation agents in conjunction with inhibitors of EDNRs may rebalance ET-axis-mediated cellular signalling to a more normal status, thus having a therapeutic impact in human breast cancer." (PMID 19527488, 2009). "Finally, we asked whether EDN3 promoter methylation may be of clinical relevance in human breast cancer, as we have previously found for EDN3 protein expression." (PMID 19527488, 2009). "Because we found that EDN3 expression is frequently lost in breast cancer tissues, we next compared EDN1, EDN2 and EDN3 mRNA expression in breast cell lines in parallel." (PMID 19527488, 2009). "A recent study demonstrated abundant expression of EDN1 and EDN2 but complete absence of EDN3 expression in a representative set of human breast cancer cell lines." (PMID 19527488, 2009). "Initially, we screened various non-malignant epithelial tissues for EDN3 mRNA expression and also analysed its expression using a breast cancer cDNA dot blot array." (PMID 19527488, 2009). "However, a comprehensive analysis of EDN3 expression in normal and cancerous breast tissues and its potential implication in human breast cancer has not been published so far." (PMID 19527488, 2009).
breast carcinoma (continued). "Our findings support the view that an imbalanced ET-axis is of pivotal relevance in breast cancer biology and that EDN3, unlike other members of the ET-axis, may represent a novel tumour suppressor gene in the human mammary gland." (PMID 19527488, 2009). "Notably, an ET-axis expression pattern similar to that of breast cancer was recently found in cervical cancer; that is, upregulation of EDN1, EDN2, EDNRA and EDNRB expression was accompanied by downregulation of EDN3 expression in cancerous cervix as compared with normal cervical epithelium." (PMID 19527488, 2009).
cervical cancer (6 papers, 2009 to 2025). A primary or metastatic malignant neoplasm involving the cervix. "Subsequently, we found that the expression of EDN3 was decreased, but the methylation of EDN3 was increased in cervical cancer cell lines." (PMID 36824133, 2023). "In current study, we firstly detected the expression and the methylation level of EDN3 in cervical scrapings and cervical cancer cell lines, including C-33A, SiHa and CaSki cell lines." (PMID 36824133, 2023). "After that, ethynyldeoxyuridine (EdU) assay, would-healing assay, clone formation assay and transwell assay were conducted to investigate the biological function of EDN3 in cervical cancer cell lines." (PMID 36824133, 2023). "The results in cervical cancer cell lines treated with 5-Aza further confirmed that methylation mediated silencing of EDN3 in cervical cancer." (PMID 36824133, 2023). "The results showed that the expression of EDN3 in three cervical cancer cells was increased after 10 μM 5-Aza treatment and was only increased in SiHa and CaSki cells after 5 μM 5-Aza treatment." (PMID 36824133, 2023). "All these results indicated that there was a close correlation between EDN3 expression and methylation in cervical cancer cell lines." (PMID 36824133, 2023). "All these results verified that the invasion capacities of cervical cancer cells in all three cell lines were significantly inhibited by overexpression of EDN3." (PMID 36824133, 2023). "Secondly, we the measured the expression of EDN3 after 5-Azacytidine (5-Aza), a DNMT1 inhibitor, treatment in cervical cancer cell lines to investigate the effect of methylation on EDN3 expression." (PMID 36824133, 2023). "Results showed that the methylation levels of EDN3 were at high level in all cervical cancer cells (>10%), especially in SiHa and CaSki cells." (PMID 36824133, 2023). "Ethynyldeoxyuridine (EdU) assay, would-healing assay, clone formation assay and transwell assay were conducted to investigate the biological function of EDN3 in cervical cancer cell lines." (PMID 36824133, 2023). "The results revealed that the expression of EDN3 were at low level in all cervical cancer cells, especially in SiHa and CaSki cells." (PMID 36824133, 2023). "Subsequently, EdU and clone formation assays were conducted to assess the influence of EDN3 on cervical cancer cell proliferation." (PMID 36824133, 2023). "The elevated methylation levels in high-grade anal lesions indicated its association with the progression of dysplastic and neoplastic lesions as shown by a previous study that endothelin 3 (EDN3) silencing by methylation promotes cervical cancer cell proliferation and invasion." (PMID 41465216, 2025). "In our studies we confirmed that methylation mediated silencing of EDN3 in cervical cancer." (PMID 36824133, 2023). "Subsequently, we investigated that whether there is an influence of EDN3 on cervical cancer cells migration." (PMID 36824133, 2023). "Overexpression of EDN3 could inhibit the proliferation, clone formation, migration and invasion of cervical cancer cells." (PMID 36824133, 2023). "EDN3 methylation levels are high in cervical cancer patients, and EDN3 methylation may serve as a molecular marker for cervical cancer." (PMID 36824133, 2023). "Furthermore, EDN3 silencing mediated by methylation can be blocked by 5-AZA treatment in cervical cancer cell lines." (PMID 36824133, 2023). "Next, to investigate whether there was a correlation between EDN3 expression and methylation in cervical cancer cell lines, we measured the methylation levels of EDN3 by pyrosequencing." (PMID 36824133, 2023). "The results of these experiments confirmed that overexpression of EDN3 could inhibit the proliferation, clone formation, migration and invasion of cervical cancer cells." (PMID 36824133, 2023). "EDN3 played a tumor suppressive function in cervical cancer." (PMID 36824133, 2023).
cervical cancer (continued). "All results together verified that overexpression of EDN3 could inhibit the proliferation, clone formation, migration and invasion of cervical cancer cells." (PMID 36824133, 2023). "Collectively, these data indicated that methylation might mediate silence of EDN3 in cervical cancer cell lines." (PMID 36824133, 2023). "In our current study, detecting the expression and methylation level of EDN3 both in clinical samples and cervical cancer cell lines, we confirmed the expression of EDN3 was decreased, but the methylation level of EDN3 was increased, with the degree of cervical lesions." (PMID 36824133, 2023). "Using EdU assay, would-healing assay, clone formation assay and transwell assay, we confirmed that overexpression of EDN3 could inhibit the proliferation, clone formation, migration and invasion of cervical cancer cells." (PMID 36824133, 2023). "It suggested that EDN3 played a tumor suppressive function in cervical cancer." (PMID 36824133, 2023). "EDN3 silencing mediated by methylation can be blocked by 5-Aza, a DNMT1 inhibitor, treatment in cervical cancer cell lines." (PMID 36824133, 2023). "EDN3 silencing mediated by methylation can be blocked by 5-Azacytidine (5-Aza), a DNA methyltransferase 1 (DNMT1) inhibitor, treatment in cervical cancer cell lines." (PMID 36824133, 2023). "The detail mechanism of EDN3 suppression of cervical cancer has not been elucidated in this study and will be further investigated in our future work." (PMID 36824133, 2023).
Hypertension (6 papers, 2014 to 2024). The presence of chronic increased pressure in the systemic arterial system. "GWAS variant rs16982520, located within ZNF831, is associated with hypertension, systolic blood pressure and mean arterial pressure and interacts directly with EDN3 and four direct interactors of the putative regulatory region (GNAS, RP4-614C15." (PMID 38885195, 2024). "Endothelin-3 signaling and other putative signaling mechanisms should be investigated in the central and peripheral nervous system in the context of hypertension." (PMID 35784866, 2022). "Edn3 was identified as a candidate gene for hypertension in humans via a GWA study." (PMID 25259444, 2014). "This list included Angptl7, Hdc, Cndp2, Dna2, Edn3, which were up-regulated in the hypertensive mice and may have a physiological role in the regulation of high blood pressure." (PMID 25259444, 2014).
Waardenburg-Shah syndrome (6 papers, 2013 to 2025). Waardenburg-Shah syndrome (WSS) is a neurocristopathy characterized by the association of Waardenburg syndrome (sensorineural hearing loss and pigmentary abnormalities) and Hirschsprung disease. "Mutations in the human genes encoding the endothelin ligand-receptor pair EDN3 and EDNRB cause Waardenburg-Shah syndrome (WS4), which includes congenital hearing impairment." (PMID 39868048, 2025). "Type IV or Waardenburg-Shah syndrome is associated with mutations in either Sry BOXIO transcription factor (SOX10), at 22q13.1, Endothelin 3 (EDN3), at 20q13, or Endothelin Receptor Type B (EDNRB) on chromosome 13q22.321,22." (PMID 30854529, 2017). "In humans, mutations in EDN3 and EDNRB cause Waardenburg-Shah syndrome (Waardenburg syndrome type IV) hallmarked by defects in pigmentation and neonatal bowel obstructions." (PMID 24857848, 2014).
glioma (3 papers, 2022 to 2026). A benign or malignant brain and spinal cord tumor that arises from glial cells (astrocytes, oligodendrocytes, ependymal cells). "Genes associated with the neuronal differentiation pathway (Pcsk9, Runx1, Cebpb, Fzd4, Wnt7a, Ascl1, Fzd2, Edn3, Olig2, and Gpc2), gliomas (Shc1, Cdk4, E2f2, and Ccnd1), and cell cycle (Bub1b, Bub, Ccnb1, Ccnb2, and Cdc20) were significantly downregulated." (PMID 36147849, 2022).
mastitis (3 papers, 2015 to 2023). Inflammation of breast tissue during lactation or postpartum due to an obstructed duct or infection. "The comparison between these candidate QTL regions and known genes suggested that NPFFR2, SLC4A4, DCK, LIFR, and EDN3 may be considered as candidate genes for mastitis susceptibility." (PMID 26087655, 2015). "Therefore, NPFFR2, SLC4A4, DCK, LIFR, and EDN3 are candidate genes for susceptibility to mastitis." (PMID 26087655, 2015). "Furthermore, the comparison between these candidate QTL regions and known genes suggests that NPFFR2, SLC4A4, DCK, LIFR, and EDN3 may be considered as candidate genes for mastitis susceptibility." (PMID 26087655, 2015). "A sequence-based association study of clinical mastitis to refine previously detected QTL regions suggested NPFFR2, SLC4A4, DCK, LIFR, and EDN3 as candidate genes for mastitis susceptibility." (PMID 27014337, 2016).
bacteremia (2 papers, 2019 to 2024). "Single-nucleotide polymorphisms near the EDN3 gene have been associated with blood pressure regulation, and reduced risk of hospitalized bacteremia events in end-stage renal disease patients." (PMID 38904098, 2024). "The minor allele of rs260741, rs197173, and rs926632 in EDN3 was associated with a reduced risk of hospitalized bacteremia events in patients with end-stage renal disease (ESRD)." (PMID 31167651, 2019). "The minor allele of rs260741, rs197173, and rs926632 SNPs of EDN3 were found to be associated with reduced risk of hospitalized bacteremia events." (PMID 31167651, 2019). "The minor allele of rs260741, rs197173, and rs926632 in EDN3 were associated with reduced risk of hospitalized bacteremia events in ESRD patients." (PMID 31167651, 2019). "The rs260741, rs6064764, rs197173, and rs926632 of EDN3 genotypes showed a significant association with hospitalized bacteremia events." (PMID 31167651, 2019). "Patients carrying the minor allele of EDN3 rs260741 (AA/AG vs. GG), rs197173 (TT/TG vs. GG), and rs926632 (CC/CT vs. TT) had a lower risk of hospitalized bacteremia events (genotype model, dominant model, and allelic model P value < 0.05)." (PMID 31167651, 2019).
cardiac hypertrophy (2 papers, 2023 to 2024). "For example, while endothelin-3 (Edn3), which is involved in the development of cardiac hypertrophy, was similarly upregulated in the hearts of mice on either diet, 1 week after TAC, Edn3 expression levels began to decline in the absence of dietary BCAAs." (PMID 37669116, 2023). "Edn3 and Tgfb2, encoding Endothelin 3 and TGF-β2, respectively, may induce cardiac hypertrophy, whereas GDF15 induces cellular senescence and inflammation." (PMID 39119147, 2024).
deafness (2 papers, 2016 to 2020). An inherited or acquired condition characterized by the complete loss of the ability to hear from one or both ears. "While the linkage of these phenotypes to EDN3 in SAC was previously unsuspected, studies have suggested EDN3 is linked to white pelage in wild cats and the co-occurrence of deafness (congenital deafness) and white pigmentation is a common observation in domestic animals." (PMID 32616020, 2020). "Phenotypes caused by the genes endothelin 3 (END3), endothelin receptor B (EDNRB), microphthalmia-associated transcription factor (MITF), paired box 3(PAX3), SRY-box 10 (SOX10), and snail homolog 2 (SNAI2) can result in decreased melanocytes, white coat color, and ultimately deafness." (PMID 27698666, 2016).
endometrial cancer (2 papers, 2023 to 2024). Primary or metastatic malignant neoplasm involving the endometrium (mucous membrane that lines the endometrial cavity). "Published experimental works focus on their effects on endothelin-1 and endothelin receptors, but little is known about endothelin-3, particularly in endometrial cancer." (PMID 36542159, 2023). "The microarray experiment and RT-qPCR in this study indicated that EDN3 is downregulated in all endometrial cancer grades." (PMID 36542159, 2023). "The degree of EDN3 methylation was also assessed, which increased with the progression of endometrial cancer." (PMID 36542159, 2023). "In our study, we focused particularly on endothelin-3 as information regarding its epigenetic silencing has emerged in other cancers, but not in endometrial cancer." (PMID 36542159, 2023).
glioblastoma (2 papers, 2016 to 2021). The most malignant astrocytic tumor (WHO grade IV). "EDN3-dependent signalling was shown to counteract the inhibitory effect of TNC on glioblastoma cell adhesion to FN40." (PMID 27905407, 2016).
papillary thyroid cancer (2 papers, 2021 to 2023). "In addition, reduced EDN3 expression was associated with the progression of papillary thyroid cancer." (PMID 36824133, 2023).
breast tumour (1 paper, 2009). "This will unravel in detail the inter-relationship between EDN3 expression loss and upregulation of EDN1/2 and EDNRA/B as well as its association with breast tumour progression." (PMID 19527488, 2009).
cervical adenocarcinoma (1 paper, 2023). An adenocarcinoma arising from the cervical epithelium. "Whether there is any association between EDN3 and cervical adenocarcinoma is still unknown." (PMID 36824133, 2023).
cervical squamous cell carcinoma (1 paper, 2023). A squamous cell carcinoma arising from the cervical epithelium. "In our current study, using the datasets from Gene Expression Omnibus (GEO) and the Cancer Genome Atlas (TCGA) databases, we found that endothelin 3 (EDN3) was downregulated and hypermethylated in cervical squamous cell carcinoma (CSCC)." (PMID 36824133, 2023).
colitis (1 paper, 2022). Inflammation of the colon. "These include chemotherapeutics, colitis, and disrupted endothelin-3 signalling, all of which decrease CMC frequency." (PMID 35317196, 2022).
enterocolitis (1 paper, 2019). An inflammatory process affecting the small intestine and colon. "A previous study on EDN3 and EDN receptor type B (EDNRB) knockout mouse model showed that EDN3 and EDNRB were associated with severe enterocolitis." (PMID 31167651, 2019).
invasive breast carcinoma (1 paper, 2009). A carcinoma that infiltrates the breast parenchyma. "In contrast, invasive breast carcinomas showed complete loss or reduced EDN3 expression (IRS < 8) in 45.3% (68 of 150) of cases and abundant EDN3 expression in 54.7% (82 of 159)." (PMID 19527488, 2009).
lymph node metastasis (1 paper, 2009). "Patient age at diagnosis, tumour size, lymph node metastasis, histological grade and EDN3 expression were included in the model." (PMID 19527488, 2009).
malignant glioma (1 paper, 2023). A grade III or grade IV glioma arising from the central nervous system. "EDN3 promotes cell apoptosis and inhibits cell invasion and migration in malignant glioma cells." (PMID 36824133, 2023).
melasma (1 paper, 2022). "TheWNT3A, EDN3, ESR2, PTG2, MMP1, and SOD2 genes were up-regulated, whereas the COL4A1, CSF2, DKK3, COL7A1, TIMP4, CCL2, and CDH11 genes were down-regulated in melasma skin fibroblasts when compared to the ones from adjacent healthy skin." (PMID 35840442, 2022).
metabolic syndrome (1 paper, 2019). A cluster of metabolic risk factors for CARDIOVASCULAR DISEASES and TYPE 2 DIABETES MELLITUS. "We investigated the correlation of DNA methylation with expression of seven genes (WDR27, GNAS, DOK7, EDN3, CMYA5, PRKG1, and MCF2L) selected on the basis of their known functions in metabolic syndrome, and their locations in functional genomic regions." (PMID 31170227, 2019). "Seven genes (WDR27, GNAS, DOK7, EDN3, MCF2L, PRKG1, and CMYA5) were selected based on genomic location and relevance to metabolic syndrome." (PMID 31170227, 2019).